DLL3 (delta like canonical Notch ligand 3)
Diseases named in the same sentence as DLL3 in open-access papers (continued):
Sharing a sentence is not in itself a finding about the gene and the disease.
glioma (continued). "Interestingly, we found that a subset of TAMs also express genes encoding the markers of glioma cells, such as GFAP, DLL3, OLIG1 and SOX4." (PMID 34805184, 2021). "Despite these findings, RNA‐seq from a Nf1;Tp53CKO mouse model of glioma where the tumors also lack ASCL1 revealed that although some Notch related genes (Dll3, Hes5, Hes6) were decreased, expression of many of the Wnt related genes seemed unaffected by the loss of ASCL1." (PMID 32573857, 2020). "Integrated DNA and RNA analysis of low-grade and high-grade proneural gliomas identified increased expression and gene amplification of several genes including GLIS3, TGFB2, TNC, AURKA, and VEGFA in proneural GBMs, with corresponding loss of DLL3 and HEY2." (PMID 20838435, 2010). "DLL3 exhibits broad expression across neuroendocrine carcinomas (NECs), encompassing high-grade pulmonary, mammary, pancreatic, prostatic, and intestinal NECs, as well as low-grade gliomas and neuroblastomas, establishing its viability as a surface antigen for targeted therapies." (PMID 40496850, 2025). "Interestingly, in gliomas DLL3 overexpression is not a consequence of DLL3 mutations or gene amplification." (PMID 34926242, 2021). "For example, an in vitro study demonstrated that METTL3 can activate the Notch pathway and facilitate glioma development by regulating the pathway targets NOTCH3, delta-like protein 3(DLL3), and HES1." (PMID 37189411, 2023). "Many of them, such as CDHR1, DLL1, DLL3 and SCG3, have been reported to be potential therapeutic targets for glioma treatment." (PMID 35456975, 2022). "In brain tumors, DLL3 has been shown to be most intensely and homogeneously overexpressed in IDH-mutant gliomas compared to other glioma subtypes." (PMID 34926242, 2021). "In malignant glioma cells, OLIG2/DLL3 and AQP4/CLU distinguish tumor cells exhibiting transcriptomic features of oligodendrocytes and astrocytes, respectively." (PMID 34692159, 2020). "Seventeen genes represent active Notch signaling components, including NOTCH1, NOTCH3, HES1, MAML1, DLL-3, and JAG2, which are enriched in the proneural subtype of glioma stem cells." (PMID 26599017, 2015). "DLL3 has also been reported on; it was found that high levels of the DLL3 protein is prognostic in IDH1 mutant gliomas but not in GBM, which tracks well in our results." (PMID 39941811, 2025). "METTL3 can activate Notch pathway and facilitate glioma occurrence through regulating its direct targets NOTCH3, DLL3, and HES1, and Notch pathway genes may serve as the potential treatment targets for glioma." (PMID 34589481, 2021). "METTL3 was positively associated with DLL3, HES1, and NOTCH3 expressions in the CGGA glioma dataset, but not the GSE16011 glioma dataset (0.23 < cor < 0.34, p < 0.05)." (PMID 34589481, 2021). "In this study, some important glioma-related genes were not differentially expressed in PDGFRA-overexpressing canine gliomas, including HIF1-α, CTLA4, DLL3, and TNFRSF12A, important mediators of angiogenesis, immune evasion, self-renewal, and invasion in the tumor microenvironment." (PMID 29352201, 2018). "Finally, we demonstrate the potential expanded utility of DLL3-targeted therapies beyond NENs, finding robust expression of DLL3 in gliomas, medulloblastomas, and melanomas, among other non-neuroendocrine cancer types." (PMID 39874041, 2025). "From other findings and our cell experiment results, we demonstrated that METTL3 can activate Notch pathway and facilitate glioma occurrence through regulating its direct targets NOTCH3, DLL3, and HES1, and Notch pathway genes may serve as the potential treatment targets for glioma." (PMID 34589481, 2021). "Two hundred and eighty targets were upregulated or downregulated in 14 cancer types, among which BAX, CENPK, DLL3, and NOTCH3 showed a consistent upregulation in multiple cancers and glioma, indicating that these genes may play a carcinogenic role in a variety of cancers." (PMID 34589481, 2021).
glioma (continued). "Collectively, these findings and other previous report demonstrated that METTL3 can activate Notch pathway and facilitate glioma occurrence through regulating its direct targets NOTCH3, DLL3, and HES1, and Notch pathway genes may serve as the potential treatment targets for glioma." (PMID 34589481, 2021). "It has been proposed that glioma CSCs express differentiation markers similar to those in normal glia and neurons, such as of oligodendrocytes (ASCL1, OLIG2 and DLL3), astrocytes (GFAP), neurons (β-tubulin III, SYT1 and SLC12A5), and markers of inflamed astroglial cells (SERPINE1, TGFB1 and RELB)." (PMID 31661894, 2019).
neuroendocrine tumors (30 papers, 2019 to 2026). "DLL3 expression in neuroendocrine neoplasms is associated with tumor progression and poor clinical outcomes." (PMID 37509621, 2023). "DLL3, one of the ligands of the Notch signaling pathway located in the cell membrane of tumor cells, is often expressed in neuroendocrine tumors and exerts an inhibition of DLL1/NOTCH interaction, causing an inhibition of the Notch pathway." (PMID 37893184, 2023). "In contrast, in cells of SCLC and other high-grade neuroendocrine tumors, DLL3 is highly up-regulated and aberrantly expressed on the cell surface, leading to abnormal growth of neuroendocrine tumor cells." (PMID 40510353, 2025). "Recent advancements in novel therapies, including peptide receptor radionuclide therapy (PRRT) and Delta-like ligand 3 (DLL3) bispecific T-cell engager (BiTE) therapies, are also promising treatment strategies for neuroendocrine tumors." (PMID 40747199, 2025). "Despite advances in SCLC and NEPC, the role for DLL3-targeted therapies in patients with other extrapulmonary neuroendocrine neoplasms remains underexplored." (PMID 41264896, 2025). "We examined a series of NENs of all types as well as several non-neuroendocrine neoplasms using immunohistochemistry for DLL3 and SEZ6." (PMID 40699376, 2025). "DLL3 represents one of the ligands of the notch signaling pathway and is expressed in several tumor entities including small lung cancer and neuroendocrine tumors." (PMID 38730739, 2024). "Neuroendocrine carcinomas, such as SCLC, express DLL3 in more than 85% of tumors, and in the digestive system, DLL3 is overexpressed in neuroendocrine carcinomas compared with neuroendocrine tumors." (PMID 38958823, 2024). "Despite these results, the role of DLL3 in other non-neuroendocrine tumors like PDAC remains unexplored." (PMID 37893184, 2023). "DLL3 expression has also been described in various extrapulmonary neuroendocrine neoplasms (particularly high-grade carcinomas), such as bladder, cervix, anus, prostate, and bile duct neuroendocrine carcinomas." (PMID 37509621, 2023). "DLL3 is an inhibitory ligand of the Notch signaling pathway, which has been found to be expressed on the surface of a variety of different neuroendocrine neoplasms, including NEPC 24,25,45." (PMID 38196594, 2023). "The urgent need for new therapeutic targets pushed our team to study DLL3 in a non-neuroendocrine tumor like PDAC." (PMID 37893184, 2023). "Delta-like canonical Notch ligand 3 is a novel therapeutic target for neuroendocrine tumors, having a huge field of pharmacologic development that has not been formally studied in non-neuroendocrine neoplasms." (PMID 37893184, 2023). "DLL3 is overexpressed on the cell surface of neuroendocrine tumor cells in about 80% of SCLCs, whereas it is normally expressed in the cytoplasmic area in healthy cells." (PMID 36530878, 2022). "Preclinical studies support the development of novel therapies that target DLL3 in SCLC and possibly other neuroendocrine tumors, and have demonstrated that targeting of DLL3 using an ADC approach inhibits tumor growth." (PMID 36381237, 2022). "Collectively, these data provide a foundation for vigilance about future consideration of clinical development of DLL3-targeted immunotherapeutic agents for neuroblastoma and other potentially other DLL3-expressing neuroendocrine tumors." (PMID 36381237, 2022). "At this point, DLL3 has been defined as a potential therapeutic target in SCLC or neuroendocrine tumors." (PMID 34425876, 2021). "Demographics and clinical and pathological features of low-grade neuroendocrine tumors (82/155) based on high DLL3 expression." (PMID 34568063, 2021). "Demographics and clinical and pathological features of high-grade neuroendocrine tumors (73/155) based on high DLL3 expression." (PMID 34568063, 2021). "Demographics and clinical and pathological features of all neuroendocrine tumors based on high DLL3 expression." (PMID 34568063, 2021).
neuroendocrine tumors (continued). "Delta-like protein 3 (DLL3) is a transmembrane protein that promotes the development of neuroendocrine tumours through its reciprocity with the Notch pathway." (PMID 32847588, 2020). "Notch signaling is downregulated during neuroendocrine tumor growth and is inhibited by DLL3 expression." (PMID 31215500, 2019). "Our aim was to investigate four different antibodies for their reliability to detect DLL3 expression in high-grade neuroendocrine tumors of the lung and well characterized cell cultures." (PMID 31109352, 2019). "In this study, the expression of DLL3 was analyzed using different DLL3 antibodies in high-grade neuroendocrine tumors of the lung and cell cultures." (PMID 31109352, 2019). "Expression of DLL3 is known to be a feature of pulmonary high-grade small-cell and large-cell neuroendocrine carcinomas and high-grade prostate neuroendocrine carcinomas as well as other neuroendocrine neoplasms." (PMID 40699376, 2025). "Despite the cessation of trials with Rova-T as an ADC approach using a PBD dimer to target DLL3, this remains a conceivable target in neuroblastoma and other neuroendocrine tumors due to its relatively restricted normal expression and moderate expression in preclinical PDX models." (PMID 36381237, 2022). "DLL3 is an atypical Notch pathway ligand that, in contrast to canonical Notch ligands, is predominantly localized to the Golgi in normal cells but exhibits aberrant cell surface expression in neuroendocrine tumor cells, where its functional role on the surface is an area of active research." (PMID 40507301, 2025). "DLL3/Notch binding prevents dislocation of the receptor on the cell surface and emerges on the cell membrane when it is pathologically overexpressed, resulting in aberrant growth of neuroendocrine tumor cells, including SCLC and large-cell neuroendocrine carcinoma (LCNEC)." (PMID 36530878, 2022). "In conclusion, this study provides a comprehensive overview of DLL3 and SEZ6 expression in the spectrum of neuroendocrine neoplasms, revealing distinct patterns across different tumor types and grades." (PMID 40699376, 2025). "Several DLL3-targeted agents are being evaluated in ongoing clinical studies of SCLC and other neuroendocrine tumors." (PMID 38126617, 2023). "Other DLL3-targeting TCEs and molecules, including BI 764532, QLS31904, RO7616789, and PT217, have entered phase 1 clinical trials and are being evaluated in patients with DLL3-positive SCLC and other neuroendocrine tumors (NETs)." (PMID 37355629, 2023). "DLL3 is considered a novel target for SCLC treatment; increased expression of DLL3 was found in SCLC and other neuroendocrine tumors, with lower expression levels in most normal tissues." (PMID 36261831, 2022). "Delta-like protein 3 (DLL3) is a ligand for the Notch receptor and a promising therapeutic target molecule for small cell lung cancer (SCLC) and other neuroendocrine tumors." (PMID 35884975, 2022). "Delta-like protein 3 (DLL3) is highly expressed in solid tumors, including neuroendocrine carcinomas/neuroendocrine tumors (NEC/NET)." (PMID 34354225, 2021). "Delta-like ligand 3 (DLL3) is an inhibitory Notch pathway ligand that is highly upregulated and aberrantly expressed on the cell surface in SCLC and other high-grade neuroendocrine tumors." (PMID 31215500, 2019). "Delta-like ligand 3 (DLL3) is an inhibitory Notch ligand that is highly expressed in SCLC and other neuroendocrine tumors but minimally expressed in normal tissues." (PMID 31215500, 2019). "These DLL3-specific agents are now being evaluated in several ongoing clinical studies in SCLC and other neuroendocrine tumors." (PMID 31215500, 2019). "In 43 non-neuroendocrine neoplasms of the GI tract, pancreas, and liver and 10 non-neuroendocrine thyroid carcinomas, there was only weak focal reactivity for DLL3 in three and two cases, respectively, and for SEZ6 in one case each." (PMID 40699376, 2025).
neuroendocrine tumors (continued). "Two well-differentiated grade 2 thymic neuroendocrine tumors had positive staining for both DLL3 and SEZ6, with moderate intensity in about 10% of cells for DLL3 (H-score 20 for both), and 20% strong and 40% moderate positivity of cells for SEZ6 (average H-score 70, range 60–80)." (PMID 40699376, 2025). "DLL3 is a cell surface protein expressed in neuroendocrine tumors (notably small cell lung cancer (SCLC) and NEPC) but not in normal adult tissues, making it an ideal immunotherapeutic target in this context." (PMID 40507301, 2025). "Antibody-drug conjugates are emerging as a method of treatment for malignancies, including MCC.CD56 is a glycoprotein expressed on neuroendocrine tumors, and has been shown to be expressed on MCC tumors.DLL3 has also been proposed as a target for antibody-drug conjugates." (PMID 39136002, 2024). "In contrast, DLL3 expression is not observed at a high prevalence in low-grade, well-differentiated neuroendocrine tumors (NET)." (PMID 34354225, 2021). "The last group is delta-like protein 3 (DLL-3), a ligand in the Notch signalling pathway that is highly expressed in tumours of neuroendocrine origin, such as neuroendocrine carcinomas (NEC) or neuroendocrine tumours (NET), which are related to cell cycle development and death signaling." (PMID 36874351, 2023). "DLL3 is highly expressed in SCLC and other neuroendocrine tumors, and it has low to no expression in most normal tissues." (PMID 31215500, 2019).
neuroendocrine carcinoma (22 papers, 2017 to 2025). A malignant neuroendocrine neoplasm composed of cells containing secretory granules that stain positive for NSE and chromogranin. "Delta-like ligand 3 (DLL3) serves as a therapeutic target in solid tumors, particularly in neuroendocrine cancers, where its expression is linked to aggressive tumor behavior and poor prognosis." (PMID 40496850, 2025). "Given the continued development and expansion of DLL3-targeted therapies, we sought to characterize the expression of DLL3 and identify its clinical and molecular correlates across diverse neuroendocrine and non-neuroendocrine cancers." (PMID 39874041, 2025). "We observed the expression of DLL3 in a collective of primary resected 479 non-neuroendocrine carcinomas including colorectal, gastric, pancreatic, and pulmonary carcinomas." (PMID 40153138, 2025). "DLL3 expression was particularly prominent in high-grade neuroendocrine carcinomas, including lung NECs and Merkel cell carcinomas." (PMID 40699376, 2025). "In conclusion, by exploring the clinical and biological correlates of DLL3 expression, we reveal the expanded utility of DLL3-targeted therapies across diverse neuroendocrine and non-neuroendocrine cancers." (PMID 39874041, 2025). "DLL3-targeted therapies have recently shown robust clinical efficacy in aggressive neuroendocrine cancers, positioning them to fulfill a great unmet need in these settings." (PMID 39874041, 2025). "Altogether, we demonstrate that DLL3 represents an attractive target for subsets of neuroendocrine and non-neuroendocrine cancers and uncover opportunities for future therapeutic strategies." (PMID 39874041, 2025). "DLL3 is an inhibitory Notch ligand overexpressed in high-grade neuroendocrine carcinomas, including SCLC and some EP-NECs." (PMID 40217714, 2025). "Here, we examine the clinical and biological correlates of DLL3 expression in both neuroendocrine and non-neuroendocrine cancers." (PMID 39874041, 2025). "Delta-like protein 3 (DLL3) has been identified as a tumor-specific cell surface marker on neuroendocrine cancers, including SCLC." (PMID 36951942, 2023). "The Delta-like ligand-3 (DLL3), an atypical Notch ligand, which is highly expressed by neuroendocrine cancer cells, is currently being explored as a therapeutic target in SCLC." (PMID 37370786, 2023). "Our findings may stimulate the development and application of DLL3-targeted therapies, as well as other precision therapies, in neuroendocrine cancers and beyond." (PMID 39874041, 2025). "Finally, we wanted to explore the expression landscape of DLL3 in non-neuroendocrine carcinomas, in which DLL3 expression was exceedingly rare (and if found, mostly weak), which argues that expression of DLL3 is largely restricted to NEN." (PMID 40153138, 2025). "However, since GEP-NET and non-neuroendocrine carcinomas rarely express DLL3, it appears to be a less promising target for these neoplasms." (PMID 40153138, 2025). "The Venn diagram showed that there were only two genes exclusively overexpressed in the high-grade MTC subset: DLL3, an inhibitory NOTCH pathway ligand associated with neuroendocrine carcinomas, and CENPA, a protein-coding gene associated with centromere function." (PMID 38958823, 2024). "DLL3 is broadly expressed in neuroendocrine carcinomas (NECs), including lung NEC, gastrointestinal pancreatic, bladder, prostate, and cervical NECs." (PMID 40066092, 2025). "Our study aimed to determine whether DLL3 expression is generally exclusive to NEC or if similar expression levels are also present in NET or non-neuroendocrine carcinomas." (PMID 40153138, 2025). "DLL3 was common in pulmonary carcinoids (41.5%), but rare in GEP-NET (5.1%) and non-neuroendocrine carcinomas (1.3%)." (PMID 40153138, 2025). "To address these questions, we analysed DLL3 expression in a large multicentric cohort of 1294 NET and NEC (301 pulmonary, 993 extrapulmonary), along with 67 matched NEN metastases and 479 non-neuroendocrine carcinomas." (PMID 40153138, 2025).